ICE1 (interactor of little elongation complex ELL subunit 1)
Description:
Component of the little elongation complex (LEC), a complex required to regulate small nuclear RNA (snRNA) gene transcription by RNA polymerase II and III. Specifically acts as a scaffold protein that promotes the LEC complex formation and recruitment and RNA polymerase II occupancy at snRNA genes in subnuclear bodies.
Synonyms: KIAA0947
Tractability: PROTAC: ubiquitination databases record sites on it.
Gene: Protein-coding gene on chromosome 5 (5,420,664 to 5,490,220, forward strand). Ensembl gene ENSG00000164151.
Subcellular location: Nucleus; Nucleus, Cajal body
Subcellular location (Human Protein Atlas): Nuclear bodies; Nucleoplasm
Pathways (Reactome):
Gene expression (Transcription): RNA polymerase II transcribes snRNA genes
Gene Ontology:
Molecular function: protein binding; protein-macromolecule adaptor activity
Biological process: positive regulation of intracellular protein transport; positive regulation of protein-containing complex assembly; positive regulation of transcription by RNA polymerase III; snRNA transcription by RNA polymerase II; snRNA transcription by RNA polymerase III; positive regulation of snRNA transcription by RNA polymerase II
Cellular component: Cajal body; euchromatin; histone locus body; nuclear body; nucleoplasm; nucleus; transcription elongation factor complex
Genetic constraint (gnomAD): Loss-of-function variants: 47 observed, 139.86 expected, observed/expected ratio (o/e) 0.34, 90% interval 0.26 to 0.43. The upper end of that interval is the gene's LOEUF score, 0.43, which puts it in group 1 of 6, group 1 being the genes least tolerant of losing a copy. Missense variants: 2,466 observed, 2,514.7 expected, observed/expected ratio (o/e) 0.98, 90% interval 0.95 to 1.01. Synonymous variants: 927 observed, 934.58 expected, observed/expected ratio (o/e) 0.99, 90% interval 0.94 to 1.05.
Homologues: Orthologues: chimpanzee ICE1 (99% identical), macaque ICE1 (95% identical), dog ICE1 (71% identical), rabbit ICE1 (70% identical), mouse Ice1 (61% identical), rat Ice1 (60% identical), pig ICE1 (59% identical), zebrafish ice1 (18% identical), Drosophila melanogaster Paf-AHalpha (2% identical). Paralogues in human: PAFAH1B3 (3% identical), PAFAH1B2 (2% identical).
Diseases named in the same sentence as ICE1 in open-access papers:
ICE1 is named in the same sentence as 10 diseases in open-access papers, as found by Europe PMC text mining. Sharing a sentence is not in itself a finding about the gene and the disease. The quoted sentences say what the papers report.
lung adenocarcinoma (1 paper, 2021). A carcinoma that arises from the lung and is characterized by the presence of malignant glandular epithelial cells. "The present study identified a novel competing endogenous RNA axis (SVIL‐AS1/miR‐103a/ICE1) that regulated lung adenocarcinoma (LUAD) chemotherapy resistance." (PMID 34264003, 2021).
lung carcinoma (1 paper, 2021). "However, the molecular mechanisms of ICE1 in regulating DNA damage of lung cancer cells still need to be further studied." (PMID 34264003, 2021).
lymphoma (1 paper, 2024). A malignant (clonal) proliferation of B- lymphocytes or T- lymphocytes which involves the lymph nodes, bone marrow and/or extranodal sites. "Treatment of lymphoma cells with CBD, THC, and WIN induced inflammatory form of programmed cell death, as seen by the significant change in the activity of the inflammatory markers ICE-1 and COX (n = 5, p < 0.05)." (PMID 38672512, 2024). "The overproduction of COX and ICE-1 in cancer cells treated with CBD, THC, and WIN implies the possibility of the induction of an inflammatory pathway involved in cannabinoid-induced decrease in lymphoma cell viability." (PMID 38672512, 2024).
cancer (4 papers, 2013 to 2025). A tumor composed of atypical neoplastic, often pleomorphic cells that invade other tissues. "“Reducing IL-1beta and IL-18 production by inhibition of ICE-1 is one promising strategy...” in cancer treatment that was outlined already in 2001 by Randle's group in München." (PMID 23594434, 2013). "We found telomere maintaining genes (TERF2, CTC1, and ACD), genes involved in zinc homeostasis (MTF1 and SLC30A9), transcription elongation factor complex components (ICE1, ICE2, ELL), and BCL6 corepressors (BCOR, BCORL1) uniquely invoked in TNBC cancers." (PMID 40700427, 2025).
ICE1 also shares sentences with these, for which no sentence is quoted: acute pancreatitis (1 paper); Cerebellar hypoplasia (1); gastric cancer (1); glioblastoma (1); hypospadias (1); neuroblastoma (1).